WT1 (WT1 transcription factor)
Diseases named in the same sentence as WT1 in open-access papers (continued):
Sharing a sentence is not in itself a finding about the gene and the disease.
tumor (continued). "Immunohistochemically, tumor cells express a panel of mesothelial markers including Calretinin, CK5/6, WT1, and D2-40." (PMID 40432917, 2025). "Here, we focused on complex gene engineering of TCR-T cells with specificity for Wilms’ Tumor 1 (WT1), a tumor antigen overexpressed by a wide range of hematological and solid tumors." (PMID 40735486, 2025). "Activates WT1‐specific CD4+/CD8+ T cells, modulates the tumor microenvironment, and reduces Treg cells and MDSCs." (PMID 41200280, 2025). "Tumor cells were positive for pancytokeratin and variably positive for EMA, GATA3, CD10, WT1, and ER." (PMID 40959354, 2025). "WT1 and FOXA1 silencing impaired the tumor-sphere forming ability of neurospheres treated with TMZ, decreased the spheroid frequency and reduced the mRNA expression of the stem markers NANOG, OCT4 and SOX2 (Fig. 4Gleft and right panels)." (PMID 40399259, 2025). "Based on the result derived from GEPIA, the expression of genes, including Cd3e, Cd274 (PDL-1), Wt1, Fate, Gbp2, and Cybb were significantly upregulated in the GBM tumor compared to the normal brain." (PMID 41282050, 2025). "The patient obtained an omental biopsy that showed tumor cells positive for pan cytokeratin (AE1/AE3), calretinin, and Wilms Tumor 1 gene (WT-1)." (PMID 41194819, 2025). "In summary, before the absence of molecular and methylation profile confirmation, the microscopic morphology combined with WT1, ETV4, NUT and other immunohistochemical staining is helpful for the diagnosis and differential diagnosis of this tumor." (PMID 40255429, 2025). "Wilms’ Tumor 1 (WT1), located on chromosome 11p13, is a C2H2 zinc-finger transcription factor that was initially discovered as a tumor suppressor." (PMID 38190392, 2024). "BAP, Wilms' tumor 1 (WT1), and calretinin immunohistochemical (IHC) staining in tumor tissue are useful markers in the histopathological diagnosis of PM." (PMID 38280040, 2024). "The fusion of EWS and WT1 is characteristic for DSRCT, and systemic CHT is often used because the tumor is chemosensitive." (PMID 38975369, 2024). "ES is characterized by the uniform arrangement of small round bundles or diffuse tumor cells expressing CD99, FLI-1, Ki-67, CD38, and WT-1." (PMID 39139288, 2024). "Several studies have reported the clonal expansion of tumor-infiltrating lymphocytes specific to TAAs, such as Melan-A, MART-1, and NY-ESO-1, in patients with solid tumors and WT1-specific CD8+ T cells in the PB and BM of patients with AML." (PMID 39509060, 2024). "Despite these insights, the study of WT1 immunoreactivity remains scant in adult RCC patients, both in terms of immunoexpression patterns in RCC tumor tissues and in tumor-adjacent healthy renal tissues (HRTs)." (PMID 38929778, 2024). "Treatment with HMA in MDS results in the upregulation of previously methylated and silenced tumor genes that express antigens such as NY-ESO-1, MAGE-A3, PRAME, and WT1." (PMID 39199554, 2024). "Our current paper, regarding the comparative and integrative analysis of IHC biomarkers (WT1 and TDs) expression patterns in adult RCC cellularity, TMEs, and tumor-adjacent HRT, is, to the best of our knowledge, the first of its kind." (PMID 38929778, 2024). "The tumor cells usually exhibit positive immunohistochemical staining for CD10, WT-1, interferon-induced transmembrane protein-1 (IFITM1), ER, and PR." (PMID 39263529, 2024).
tumor (continued). "In conclusion, scarce, strictly nuclear, WT1 positivity of tumor cells, among the adult RCC specimens analyzed, as opposed to the concomitant broad prevalence of TD-reactive tumor tissues, within the same study cohort." (PMID 38929778, 2024). "Comparatively, when focusing solely on tumor-adjacent HRT expression patterns within the current IHC-stained RCC cohort, we report 6 WT1-reactive cases at this level, as well as 12 TD-reactive, respectively." (PMID 38929778, 2024). "HOXA5, WT1, and LHX2 are fibroblast specific motifs that are drivers of tumor microenvironment remodeling, and their potential targets were highly correlated with collagen - containing extracellular matrix in KEGG analysis." (PMID 38702814, 2024). "This relationship with metastasis was also found with WT1 (P = 0.017) and IL20RB (P = 7.4 × 10−06) expression in ccRCC tumours (Table EV7)." (PMID 39592856, 2024). "Tumor cells are typically positive for sex cord–stromal markers (FOXL2, inhibin, calretinin, SF1, WT1, CD56)." (PMID 38136408, 2023). "Consistent with our in vitro results, expression levels of WT1 were positively correlated with KSRP and negatively correlated with NEDD4L levels in tumor specimens from two independent ccRCC cohorts." (PMID 37580757, 2023). "Three TAA (WT-1, MUC-1 and CA125) were found highly expressed by neoplastic EOC cells, suggesting a potential role for TAAs in inducing an anti-tumor response in EOC." (PMID 37868997, 2023). "The WT1 Trio vaccine, which includes a helper peptide (WT1-332), was administered in combination in order to activate WT1-specific CD4+ T helper lymphocytes and enhance WT1-specific anti-tumor cellular immune responses." (PMID 36672344, 2023). "When incorporated into two TCR-like CARs, (HLA)-A2/GPC3- and HLA-A2/WT1-specific nanobodies selectively recognize and lyse MHC/peptide complex-expressing tumor cells both in vivo and in vitro." (PMID 38067344, 2023). "The tumor specimens including the rectal metastasis were immunohistochemically confirming a metastatic ovarian cancer using CK7, WT1 and CK20." (PMID 37099988, 2023). "Tumor cells express SF1 in 100% of the cases, inhibin in 82–98%, WT1 in 96%, CD99 in 68–86%, AE1/AE3 in 65%, and calretinin in 50–60%." (PMID 38136408, 2023). "Leveraging EPR effect, the nanomicellar form of WIP2W, referred to as M—WIP2W, exhibits enhanced intra-tumoral accumulation in WT1+ CML mice as compared to free WIP2W, leading to effective inhibition of tumor growth." (PMID 37765274, 2023). "Similar to the adult type, tumor cells express sex cord–stromal markers (SF1, inhibin, calretinin, WT1, FOXL2)." (PMID 38136408, 2023). "We found remarkable concordance in the protein expression of several key markers (BAP1, WT1, mesothelin, PD-L1, and VISTA) between the primary tumor and PDX tumors." (PMID 36380343, 2022).
tumor (continued). "Resulting WT1-specific TCR-T cells exhibited high efficacy in killing primary AML from bone marrow and ALL tumor-bearing NOD SCID gamma mice." (PMID 35356211, 2022). "So far, WT1 has been incriminated as a necessary contributor to KRAS-driven oncogenesis, demonstrating decisive regulatory roles regarding tumor cell responses (i.e., proliferation versus senescence) downstream of KRAS oncogenic signaling." (PMID 35453662, 2022). "Immunohistochemical staining shows that tumor cells are positive for CD10, cyclin D1 and vimentin and variably positive for WT1 and CD56." (PMID 36428715, 2022). "Concordance was high between PDX models and paired tumor samples for expression of key markers of interest (BAP1, WT1, mesothelin, PD-L1 and VISTA) and genomic alterations." (PMID 36380343, 2022). "Immunohistochemically, tumor cells are positive for CD10, cyclin D1 and vimentin and variably positive for WT1, FOXL2, and SF1." (PMID 36428715, 2022). "Strategies to design AML vaccines include administration of Wilms’ tumor 1 (WT1) peptide with adjuvant, DCs with WT1 tumor antigens, or DCleu." (PMID 35074008, 2022). "Accordingly, moDCs have been shown to boost WT1-specific CAR T cells in a humanized mouse model, resulting in enhanced inhibition of tumor growth." (PMID 34821951, 2022). "In one study (NCT03114631), DCs generated from blood monocytes and pulsed with tumor lysates or tumor antigens MUC1 and WT1 were injected subcutaneously to 26 patients with stage II–IV pancreatic cancer." (PMID 34290984, 2021). "The tumor cells are positive for epithelial markers (AE1/AE3, CK7, CAM5.2) and mesothelial markers (D2-40, calretinin and WT-1)." (PMID 34248850, 2021). "The largely podocyte-specific transcription factor Wilms’ tumor gene 1 (WT1) regulates the expression of SULF2 and SULF1, and children with this tumor exhibited a kidney phenotype similar to that in SULF2 and SULF1 knock-out mice." (PMID 33540508, 2021). "Histology of HGSC tumor revealed positivity for Pan-CK, markers of Mullerian epithelium (PAX8, WT1) and Ki67, as well as the markers of aggressiveness, matrix metallopeptidase (MMP) 9 and MMP2." (PMID 33530497, 2021). "A specific tumor antigen that can be targeted by peptide vaccines can be represented by the following genes EGFRvIII, IDHR132H, Wilms tumor 1 (WT1) and survivin." (PMID 34675919, 2021). "WT1, COL11A1, FGF5, and IGFL2 were up-regulated in tumor tissues, while GFAP and CD300LG were down-regulated." (PMID 33987034, 2021). "In contrast, the PD-1 expression on the tumor-infiltrating CD8+ T cells was, expectedly, much lower in the anti-PD-1-treated mice than in the WT1 peptide vaccine-treated and control mice." (PMID 34355173, 2021). "Immunobiologically, the tumor diffusely expressed estrogen receptor (ER), progesterone receptor (PR), AE1/AE3, desmin, Wilm’s tumor-1 (WT-1), CD56, and CD99." (PMID 32921307, 2020). "The cell line with a typical epithelioid morphology was checked for the expression of the markers detected in both the tumor of origin and in the PDX, and was found to express the same markers, calretinin and WT1." (PMID 33419364, 2020).
tumor (continued). "Histology confirmed the micropapillary and cribriform growth pattern with intraluminal tumor budding and positivity for PAX8 and WT1." (PMID 32317693, 2020). "To find a valuable model APC for in vitro validation of TAA Wilms’ tumor 1 (WT1)-specific TCRs, we tested four different WT1 peptide-pulsed HLA-A2+ tumor cell lines commonly used in T-cell stimulation assays." (PMID 31972992, 2020). "The tumor cells express cytokeratin 7 (CK7), cytokeratin 5-6 (CK5-6), cancer antigen 125 (CA125), estrogen (ER), progesterone (PR), Wilm's tumor gene (WT1), paired box gene 8 (PAX8), Ber-EP4, and epithelial membrane antigen (EMA)." (PMID 33062370, 2020). "In fact, WT1 increases the expression of BCL2 and enhances tumor growth and progression to metastatic disease." (PMID 33255335, 2020). "Several tumor-antigen targets, such as MSLN, WT-1, FAP and the antigens of the ErbB family are evaluated for their applicability for CAR T-cell therapy in MPM." (PMID 32582537, 2020). "In conclusion, Wt1 activates Srpk1 and Srsf1 and induces expression of angiogenic VEGF isoforms in tumor endothelium." (PMID 30641926, 2019). "Immunohistochemistry showed that the tumor cells were positive for CD10, estrogen receptor (ER), progesterone receptor (PR), Wilms tumor 1 (WT-1; nuclear staining) and smooth muscle actin (SMA)." (PMID 31010432, 2019). "WT1 peptide-pulsed DCGEM is feasible, well-tolerated, and effective for inducing anti-tumor T-cell responses." (PMID 31440238, 2019). "This is the case of the amplified oncogenes AKT1 and WT1, and of the receptor tyrosine kinase gene FLT4, which regulates lymphangiogenesis and tumor metastasization to lymphatic vessels." (PMID 31616467, 2019). "Immunohistochemistry showed that the tumor cells were positive for CD10, estrogen receptor (ER), progesterone receptor (PR), Wilms tumor-1 (WT-1) and smooth muscle actin (SMA)." (PMID 31010432, 2019). "Consistent with the primary tumour, immunohistochemical analyses also revealed focal positivity for CD99 and diffuse positivity for Bcl-2 and WT1." (PMID 31676869, 2019). "When the tumor size reached at palpable size, the three groups of mice were subcutaneously treated with pLV-GEP-WT1, pLL3.7-WT1-shRNA (plasmid expressing WT1-shRNA) with wild type WT1 and empty plasmid (as a control)." (PMID 29861465, 2018). "These engineered WT1-28z specific CAR T cells destroyed and lysed HLA-A*02:01, WT1+ tumor cells in an in vivo mice model." (PMID 30108584, 2018). "We compared the expression levels of nine hypoxia-related lncRNAs39, 40, 41 (H19, HOTAIR, NEAT1, linc-ROR, UCA1, WT1, HINCUT1, LINK-A, LincRNA-p21) between tumor central and peripheral cells." (PMID 29106390, 2018). "The numbers of Wt1-positive cells, CD31-positive cells, Wt1/CD31 double-positive cells, vessels and Wt1-positive vessels were all higher in tumours than in controls." (PMID 30374123, 2018). "Marker genes differentially expressed in the blastemal tumours relative to triphasic tumours included CM (EYA1, HOXA10, NR2F2) and PA (WT1) genes." (PMID 29040332, 2017). "Immunohistochemically, an adenomatoid tumor is positive for markers, such as CK (AE1/AE3) ΕMΑ, Cam5.2, CK 5/6, CK7, calretinin, vimentin, WT1, and HBME-1." (PMID 28003830, 2016). "The tumor cells Sp2/0-Ag14, U937 or REH were infected with the rotavirus isolates WT1-5, TRUY, WWM, WTEW or ECwt." (PMID 26828934, 2016).
tumor (continued). "Tumor cells were positive for CK7 EMA, CKAE1/AE3, CD15, CA-125, while immunoreaction for Calretinin, WT1, estrogen, and progesterone receptors, cytokeratin 20, CD10, alpha fetoprotein, CDX2, TTF1, and thyroglobulin were all negative." (PMID 27912770, 2016). "Notably, WT1 may act both as a tumor suppressor or oncogene in different context." (PMID 27481518, 2016). "Surprisingly, other tumor-suppressor genes, such as PTCH1, DAB2IP, and WT1 were included in the gained regions." (PMID 27481518, 2016). "Our patient's tumor showed a biphasic staining pattern and the larger cells had a mesotheliomatous immunoprofile with positivity for calretinin, CK7, CK5/6, and WT1 which was definitively distinct from the smaller blue cell component." (PMID 27403364, 2016). "Tumor cells Sp2/0-Ag14, U937 or REH were separately infected with rotavirus isolates WT1-5, TRUY, WWM, WTEW or ECwt at a MOI of 0.8." (PMID 26828934, 2016). "Immunohistochemical staining shows that most tumour cells are positive for MIB-1, vimentin, EMA, WT-1, and CD57; in contrast, CK7 staining exhibits weak focal positivity." (PMID 25907695, 2015). "Immunohistochemically, the tumour cells displayed expression of pan-cytokeratin AE3, progesterone receptor, Wilms’ tumour protein (WT1), and PAX8 (Paired box gene 8)." (PMID 26197800, 2015). "Immunohistochemical examination of the tumour cells displayed expression of pan-cytokeratin AE3, estrogen- and progesterone receptor, Wilms’ tumor protein (WT1), and PAX8 (Paired box gene 8)." (PMID 26197800, 2015). "Although the prognostic significance of WT1 expression in AML remains controversial, its importance as a tumor antigen and marker of minimal residual disease is growing." (PMID 25794157, 2015). "It has been previously demonstrated that the TP63/TP53L, ERG, GRHL1/Get-, HNF1A/TCF-1, SPI1/PU.1, WT1 and GLIS2, FOXM1 and FOXP3 transcription factor networks, which are mediated by HNF4A, can regulate the expression of Trop2 in tumor tissues." (PMID 25779928, 2015). "The tumor cells were diffusely positive for CD99, desmin, and WT1 and showed scattered focal positivity for cytokeratin." (PMID 24406431, 2014). "Previous work has demonstrated that WT1 regulates VEGF expression, but this is the first demonstration in an animal model that this translates into an increase in tumor angiogenesis." (PMID 24810959, 2014). "The immunohistochemical profile of the current tumor is comparable to previously reported TLFCK cases (AE1/AE3+, CK7+, PAX-2+, PAX-8+, vimentin+, EMA+, TTF-1−, TG−, CD56−, WT-1−, CD10−, and CEA−)." (PMID 25133003, 2014). "Two recent studies have addressed the consequences of WT1-RNA interactions and unmasked the effects of WT1 mutants on the splicing of the vascular endothelial growth factor (VEGF) and its consequences on angiogenesis, hematopoiesis, and tumor development." (PMID 25375204, 2014). "Looking toward adoptive T cell therapy, a WT1 /A2-specific TCR isolated from peptide-specific, allo-induced CTLs, exhibited good anti-tumor responses in a mouse xenograft model with TCR-transduced T cells." (PMID 23970885, 2013). "Cytoplasmic expression of SDC1 is positively correlated with tumor-prone proteins (WT1 and WNT1) and membranous expression of SDC1 is positively correlated with the tumor suppressor (P16)." (PMID 24373193, 2013). "All 5 tumor antigens including MAGE-A1, -A3, HER2, gp100 and WT1 were positive in 5 cases except for patient 5 in which 3 antigens were identified in the tumor." (PMID 23270484, 2012). "Some of the hypermethylated genes in TET2-wt CMML have been directly or indirectly related to cell cycle arrest, tumor suppression or myeloid differentiation (ZIC1, WT1, WNK2, MRPL41, POU4F2)." (PMID 22328940, 2012). "For the genes WT1, GATA2, and FGFR3, the expression pattern in surgically dissected tumor tissue was consistent with that in the microdissected epithelial cells." (PMID 20426842, 2010).